CEP55 (centrosomal protein 55)
Diseases named in the same sentence as CEP55 in open-access papers (continued):
Sharing a sentence is not in itself a finding about the gene and the disease.
cancer (continued). "The cancer malignancy promoting protein CEP55 is delivered by exosomes to cancer cells." (PMID 39976236, 2025). "Additionally, we investigated the relationship between CEP55 and several key cancer-related pathways." (PMID 40386043, 2025). "In summary, targeting CEP55 markedly reduces the malignant behavior of cancer cells." (PMID 40236779, 2025). "Some studies suggest that CEP55 is involved in maintaining cancer stem cell properties." (PMID 40723362, 2025). "Previous studies have shown that CEP55 is overexpressed in various cancer types." (PMID 40386043, 2025). "In conclusion, a novel molecular signature panel including the AURKA, CEP55, DTL, and TTK genes could improve early cancer detection and diagnostic accuracy, and it may contribute to the treatment outcomes of PAN-gastrointestinal cancer patients." (PMID 40723362, 2025). "We also evaluated CEP55 expression in other cancer cell lines besides organoids." (PMID 38250876, 2024). "We also determined whether the knockout of CEP55 in cancer cells could potentially elevate the expression of PD-L1, thereby enhancing sensitivity to anti-PD1 therapy." (PMID 38250876, 2024). "Moreover, it has been widely demonstrated that this CEP55 overexpression increases the malignancy of cancer cells by promoting cellular abscission, proliferation, or chromosomal instability (CIN)." (PMID 39195269, 2024). "Although previous studies have shown the association between CEP55 and cancer progression, the mechanisms of CEP55’s role in CRC are not fully understood." (PMID 38250876, 2024). "In addition, CEP55 appeared to have a positive effect on stromal scores, immune scores, and estimates in some cancer types, such as KIPAN, KIRC, and THCA, while showing a negative effect in LUSC, STAD, and STES." (PMID 37887301, 2023). "To explore whether CEP55 can be used as a marker of change in the course of cancer treatment response, we first retrieved the trend of CEP55 in the process of CRC and BRCA treatment by ROC Plotter." (PMID 37887301, 2023). "In addition, we recognized that CEP55 was part of a gene signature that was characteristic for the presence of chromosomal instability (CIN) in different cancer types (called CIN70)." (PMID 37381005, 2023). "Collectively, the results of these studies demonstrate that CEP55 could have various functions in multiple cancers." (PMID 37484531, 2023). "CBX2 showed a highly positive correlation with CEP55 at pan-cancer level." (PMID 37980163, 2023). "To further investigate the critical role of CEP55, we analyzed its expression in various cancers." (PMID 37484531, 2023). "We then investigate CBX2 and CEP55’s effects on cancer-related functional states." (PMID 37980163, 2023). "In conclusion, we confirmed that CEP55 may be closely related to immune-related genes in pan-cancer and could be further explored as a target molecule." (PMID 37887301, 2023). "CEP55 expression was correlated with at least five KEGG signaling pathways in six cancers." (PMID 37173675, 2023). "To further validate whether CBX2 and CEP55 affect malignant cell stemness, we reanalyzed the public datasets related to HCC CSC and observed that CBX2 and CEP55 levels were higher in cancer stem cells that were CD133, ALDH, or CD44-labeled." (PMID 37980163, 2023). "Overall, we found that CEP55 was widely differentially expressed in normal and tumor tissues through a comprehensive pan-cancer analysis and was closely correlated with tumor patient stage and age, further revealing the correlation between CEP55 expression and clinical prognosis." (PMID 37887301, 2023). "In conclusion, our results are consistent with previous summaries showing significant overexpression of CEP55 in most types of cancer, suggesting that CEP55 may play a potentially critical role in carcinogenesis and diagnosis." (PMID 37887301, 2023). "Clinically, CEP55 has been found to be overexpressed in many cancer types." (PMID 37887301, 2023).
cancer (continued). "Therefore, our study attempted to fill this void, and its findings revealed upregulated CEP55 expression in 20 cancers (e.g., BLCA)." (PMID 37173675, 2023). "Intriguingly, we found that CBX2 and CEP55 expressed more in para-cancerous tissue in GSE25097 compared to healthy tissue, suggesting that abnormally expressed CBX2 and CEP55 may be responsible for the development of cancer." (PMID 37980163, 2023). "Genetic variations in CEP55 were detected in 20 of the 33 cancer types." (PMID 37484531, 2023). "Beyond these cell division and signaling roles, CEP55 has recently been identified as an immunogenic tumor-associated antigen (TAA) and cancer-testis antigen (CTA), which recommend it as a potential candidate for cancer vaccine therapies." (PMID 37484531, 2023). "Besides, CEP55 shows great potential for enhancing the pluripotent stemness of cancer cells by participating in the autophagic degradation of midbody derivatives." (PMID 37274251, 2023). "The study also explored the prognostic value of CEP55 in distinct cancers." (PMID 37173675, 2023). "CEP55 may be an immune-related predictive and prognostic marker for certain cancers, including LUSC." (PMID 37173675, 2023). "Utilizing the TCGA project and publically available databases, the current study started with a differential analysis to confirm the elevated CEP55 expression in tumor versus normal tissue and correlated this expression with the grade, stage, and metastasis of several human cancers." (PMID 37175004, 2023). "Centrosomal protein 55 (CEP55) plays a significant role in specific cancers." (PMID 37173675, 2023). "According to this research, CBX2 could control CEP55 or CTNNB1 to control the characteristics of cancer stem cells that are consistent with more aggressive migration." (PMID 37980163, 2023). "The number of body-fluid samples used in this study could be expanded, as this would facilitate the validation of the mRNA and protein levels of CEP55 in pan-cancer analysis and the correlation between CEP55 and prognosis." (PMID 37173675, 2023). "Consistent with previous studies, CEP55 expression in cancer tissues was significantly higher than its expression in healthy tissues in most of the cancers analyzed, especially in BRCA, GBM, HNSC, LUAD, PAAD, and UCEC with abnormally active CEP55 mRNA and protein levels." (PMID 37887301, 2023). "Therefore, we downloaded the uniformly normalized pan-cancer dataset from the UCSC database to explore the relationship between CEP55 expression and ICP genes in cancer." (PMID 37887301, 2023). "CEP55 is a central regulator of late cytokinesis and is overexpressed in numerous cancers." (PMID 36497121, 2022). "CEP55 is in close relationship with the occurrence and development of human cancers." (PMID 35037833, 2022). "In addition, the absence of CEP55 leads to mitotic arrest and mitotic cell death in the cell cycle, and CEP55 has been proven to be an anti-mitotic drug targeting the mitotic mechanism of the cell cycle to eliminate cancer cells." (PMID 36462500, 2022). "Recently studies have demonstrated that CEP55 could promote cancer cell stemness and tumor formation through regulating the PI3K/AKT pathway." (PMID 34650590, 2021). "CEP55 was mainly expressed in the cytoplasm of ESCC cancer cells." (PMID 34104194, 2021). "CEP55 has previously been shown to regulate PI3K/AKT signaling pathway in cancer cells." (PMID 34710087, 2021). "CEP55 is a centrosomal protein that has been shown to be deregulated in a number of cancers." (PMID 33497018, 2021). "This property makes CEP55 an ideal candidate for cancer vaccine therapies." (PMID 32337246, 2020). "However, homozygous-Cep55 overexpressing mice succumbed to cancer significantly earlier (p < 0.0001) than Cep55wt/Tg and Cep55wt/wt littermates." (PMID 33087841, 2020). "Since CEP55 is highly overexpressed in multiple human cancers irrespective of its role in cell division, we asked if Cep55 overexpression causes spontaneous tumorigenesis in vivo." (PMID 33087841, 2020).
cancer (continued). "In human cancers, CEP55-overexpression results in cell transformation, proliferation, epithelial-to-mesenchymal transition, invasion, and cell migration via upregulation of the PI3K/AKT pathway through direct interaction with the p110 catalytic subunit of PI3K14,15." (PMID 33087841, 2020). "It was found that PIMREG, MTFR2, and CEP55 were overexpressed in BC and also in many other cancers." (PMID 33718103, 2020). "Recently, several studies showed that CEP55 regulated cancer progression." (PMID 32149111, 2020). "A number of studies have already described CEP55 as an overexpressed gene in cancer tissue samples." (PMID 30987631, 2019). "Based on our findings but requires further validation study, we speculate that exosomal CEP55 protein in saliva or blood could be exploited as a cancer biomarker for non-invasive mode of diagnosis and prognosis of HNSCC." (PMID 30008265, 2018). "Interestingly, several studies have illuminated that CEP55 is involved in the process of cell mobility and metastasis of cancers." (PMID 30096813, 2018). "Ingenuity pathway analysis of the genes mapped to chromosome 20 (Fig EV3J) showed enrichment in cancer‐associated processes (Fig EV3K) that may facilitate genomic instability and transformation in CEP55‐overexpressing cells." (PMID 30108112, 2018). "We have also identified CEP55 as a potential cancer exosomal marker." (PMID 30008265, 2018). "Taken together, our results may give rise to a development in the field of CEP55 biological function in promoting HCC cancer cell motility." (PMID 30096813, 2018). "These elegant findings strongly imply the significance of CEP55 in cancer propagation." (PMID 30096813, 2018). "Although not quantitative, these results provided qualitative confirmation that CEP55 could be a specific cancer exosomal membrane marker." (PMID 30008265, 2018). "This study investigated the presence of CEP55 protein in normal and cancer exosomes." (PMID 30008265, 2018). "Notably, CEP55 was shown to support the invasion and metastasis of cancer cells via upregulating MMP2 expression." (PMID 30096813, 2018). "Altogether, these findings suggest that CEP55 may play an oncogenic role in cancer development and progression." (PMID 26615423, 2016). "Moreover, high CEP55 expression was found to promote progrowth signaling pathways resulting in cancer cell metastasis and poor patient prognosis." (PMID 26615423, 2016). "Several known cancer-testis antigens are expressed, including Atad2, Cep55, and Pbk." (PMID 24621249, 2014). "In addition, CEP55 expression was strongly associated with immune cell infiltration, immune-related genes, and immune checkpoints in a variety of cancers, suggesting that CEP55 may be involved in regulating the immune landscape of some tumors." (PMID 37887301, 2023). "However, the relationship between CEP55 expression levels and prognosis, as well as their role in cancer progression and immune infiltration in different cancer types, remains unclear." (PMID 37887301, 2023). "CEP55 may have different effects on the immune microenvironment in different cancers." (PMID 37173675, 2023). "Furthermore, CEP55 could identify LUSC, and high CEP55 expression was associated with poor prognosis in LUSC patients, which partly supports the results in the pan-cancer analysis." (PMID 37173675, 2023). "Some signaling pathways may be critical for CEP55 involvement in multiple cancers, including “olfactory transduction,” “metabolism of xenobiotics by cytochrome P450,” “drug metabolism cytochrome P450,” and “cytokine-cytokine receptor interaction” signaling pathways." (PMID 37173675, 2023). "Notably, in stages II and III, CEP55 levels were highly expressed in most cancers." (PMID 37887301, 2023). "Therefore, CEP55 is considered an ideal predictor of cancer prognosis." (PMID 31612115, 2019).
cancer (continued). "We have previously published that CEP55 is a downstream target of FOXM1 oncogene and that CEP55 has been shown to be associated with ALIX and the ESCRT complex, we therefore asked if CEP55 protein may be enriched in cancer exosomes as it is known to be upregulated in cancer cells." (PMID 30008265, 2018). "Thus, the first identification of JAK2–STAT3–MMPs axis as a new target of CEP55 might help to elucidate how CEP55 drives cancer propagation, in particular, its contribution to the design of effective therapeutic strategies for treating human HCC." (PMID 30096813, 2018). "This study investigated the impact of CEP55 knockdown on CD8+ T cell immune function using coculture systems with CT26 and 3LL cancer cells." (PMID 40236779, 2025). "Computational analysis initially identified 40 cancer-active CTA genes, of which four genes (LY6K, MAGEA3, CEP55, and ATAD2) were most indicative of nodal spread." (PMID 41009820, 2025). "Centrosomal Protein 55 (CEP55) exhibits various oncogenic activities; it regulates the PI3K-Akt-pathway, midbody abscission, and chromosomal instability (CIN) in cancer cells." (PMID 39195269, 2024). "Further research identified CEP55 as a cancer-testis antigen (CTA) that is aberrantly expressed in different malignancies and a cancer vaccination candidate." (PMID 37484531, 2023). "After analyzing the correlation between CEP55 expression and different immunological components, we asked if CEP55 levels could interfere with the activity of chemotherapeutic antitumor agents to obtain guidance for chemotherapeutic selection for cancer patients with high CEP levels." (PMID 37175004, 2023). "Furthermore, CBX2 or CEP55 could potentially serve as therapeutic targets for pan-cancer." (PMID 37980163, 2023). "CEP55 was highly expressed in human HCC tissues and its overexpression correlated with poor overall survival and cancer recurrence." (PMID 37381005, 2023). "Notably, CEP55 was most likely to affect the “olfactory transduction” pathway in cancers (up to 18 cancer types) and it may could play an important role in “metabolism of xenobiotics by cytochrome P450,” “drug metabolism cytochrome P450,” and “cytokine-cytokine receptor interaction”." (PMID 37173675, 2023). "In the present study, VEGFA, RRM2, H2AFX, CHEK1, CEP55, CDCA8 and AURKA were significantly upregulated; however, VCL, TPM2 and TPM1 were significantly downregulated in cancer samples of BC." (PMID 34112125, 2021). "The results revealed that SOX9, RASA1, CEP55, and MAP4K4 were significantly higher expressed in LUAD tissues than those in adjacent cancer tissues." (PMID 33510968, 2021). "In conclusion, our study highlights that the Cep55-ESCRT pathway is essential for faithful division of NPCs, similar to some cancer cell lines in vitro, whereas abscission in most other tissues does not require Cep55." (PMID 32269212, 2020). "Enrichment analysis indicated that cell cycle, DNA replication, pathways in cancer, mTOR signaling pathway, and VEGF signaling pathway were significantly enriched in the high CEP55 expression group." (PMID 32337246, 2020). "This unique metabolic profile leads to upregulation of certain enzymes and proteins such as ALDH1, CEP55, IDO COA1 etc., which can be utilized for development of vaccine based anti-cancer immunotherapy." (PMID 31106150, 2019). "Markedly, the CTA genes ATAD2, CEP55, FANCA, KIF2C, NUF2, OIP5, and PBK had significantly positive expression correlations with the PLK1 expression in 30 cancer types (Pearson correlation, FDR<0.1)." (PMID 30631355, 2018). "To rule out this possibility, we normalized the expression value of CEP55 with key proliferation markers, KI67 and PCNA using the TCGA (The Cancer Genome Atlas) dataset (n = 492)." (PMID 30108112, 2018). "Analysis of TCGA pan‐cancer datasets showed that CEP55 expression was upregulated in tumor samples compared to normal tissues (p < 0.05)." (PMID 40236779, 2025).
cancer (continued). "Increased expression of CEP55 showed significant correlations with poor or better OS rates in various cancers, however, it was not significant in GBM patients." (PMID 40504854, 2025). "Additionally, in most malignant tumors, including HCC, CEP55 expression is significantly positively correlated with the infiltration levels of MDSCs and Th2 cells in the tumor microenvironment, leading to immune suppression." (PMID 40771801, 2025). "In conclusion, CEP55 is a multifunctional protein that significantly contributes to tumorigenesis through its roles in cytokinesis, genomic stability, cell proliferation, EMT, and cancer stem cell maintenance." (PMID 40723362, 2025). "Notably, the relationship between CEP55 and RhoA/ROCK1 signaling has been discovered, with a focus on therapeutic consequences in cancer." (PMID 39023191, 2024). "Notably, based on our study results, CEP55 was not only positively related to TMB and MSI in several cancers (SARC, etc.)but it was also positively related to neoantigens in certain cancers (ACC, etc.)." (PMID 37173675, 2023). "For partial cancers lacking normal tissue, we also used the difference in CEP55 mRNA expression on GEPIA2.0 and UALCAN directly from TCGA and GTEx data." (PMID 37887301, 2023). "Similarly, CEP55 knockdown targets and inhibits forced mitosis of MEK1/2-PLK1, leading to cancer cell death." (PMID 37887301, 2023). "We then analyzed the relationships between CEP55 expression and TMB/MSI in all cancers." (PMID 37484531, 2023). "The findings showed that CBX2-positive malignant tumors demonstrated significantly elevated levels of stemness rather than CEP55-positive." (PMID 37980163, 2023). "Notably, upregulated CEP55 expression represented poor prognostic indicators (i.e., OS, DSS, DFI, and PFI) for patients with one of four cancers: KIRP, LIHC, LUAD, and PAAD." (PMID 37173675, 2023). "Moreover, pan-cancer patients with upregulated PLK1, CEP55, FANCI, NEK2, and PTTG1 exhibited a poorer overall survival rate and disease-free survival." (PMID 37274251, 2023). "The expression of CEP55 was relevant to TMB, MSI, neoantigen counts, and immune cell infiltration in a variety of cancers, indicating that the gene may have an essential role in the immune response." (PMID 37173675, 2023). "ROC curves confirmed the ability of CEP55 mRNA expression to distinguish LUSC samples from control samples with high accuracy (AUC > 0.8), similar to the findings from the analysis of various cancers." (PMID 37173675, 2023). "The effect of CEP55 methylation on the OS of various cancers was further explored through the DNMIVD database, and the results showed that CEP55 methylation levels in CHOL, PAAD, PARD, KIRC, KIRP, CESC, and LIHC were significantly and negatively correlated with patient prognosis." (PMID 37887301, 2023). "CEP55 expression demonstrated a positive correlation with MSI in six cancers—TGCT, SARC, LUSC, OV, KIRC, and BRCA—and a negative relevance with PRAD, HNSCC, and THCA." (PMID 37173675, 2023). "Furthermore, the immunohistochemical staining results based on the HPA database revealed a significantly high positivity of the ZWINT, RRM2, NDC80, KIF4A, CEP55, CENPU, and CENPF genes in cancer tissues compared to adjacent normal tissues." (PMID 35028418, 2022). "The regulation of centrosomal protein 55 (CEP55) by hsa-miR-101-3p—-1 was the most pan-cancer conserved: a significant negative correlation was observed in 15 cancer types." (PMID 36275459, 2022). "Interestingly, the genes CDC20, CDCA8, MYBL2, C1QTNF6, CEP55, CDK1 and KIF14 were found to be more universal/common, since they mark multiple types of cancers not only in prognosis but also in diagnosis." (PMID 32489468, 2020). "CEP55, EZH2, and SLCA11 are highly expressed in HCC and play critical regulatory roles in cancers." (PMID 32104698, 2020).